EGFR (epidermal growth factor receptor)
Diseases named in the same sentence as EGFR in open-access papers (continued):
Sharing a sentence is not in itself a finding about the gene and the disease.
lung adenocarcinoma (continued). "In the current study, the prevalence of CA9 SNP rs2071676 AG and AG + GG was significantly lower in male patients with lung adenocarcinoma and the EGFR mutation of L858R expression." (PMID 32365566, 2020). "In this study, we found that ERβ5 mRNA levels were elevated in four lung adenocarcinoma cell lines harboring EGFR mutations." (PMID 33585221, 2020). "The present study was designed to evaluate the distribution frequency of antioxidant gene polymorphisms in lung adenocarcinoma, as well as its association with hotspot EGFR mutations." (PMID 32937815, 2020). "Suggested by our previous study, epidermal growth factor receptor (EFGR) mutation was associated with a lower risk of LRR in completely resected stage III-pN2 lung adenocarcinoma." (PMID 32922551, 2020). "Herein, we report the impact of EGF+61 A>G genotype over ORR and DCR to first‐generation TKIs (erlotinib and gefitinib) on 111 EGFR‐mutated Brazilian lung adenocarcinoma patients." (PMID 32881389, 2020). "Accordingly, this study aimed to summarize the factors affecting the prognosis of these patients with EGFR-mutated lung adenocarcinoma after BM." (PMID 32883221, 2020). "In conclusion, a 18F-FDG PET/CT rad score combined with clinicopathological factors can predict the survival outcomes of patients with lung adenocarcinoma with an EGFR mutation." (PMID 33262942, 2020). "EGFR exon 19 deletions are the most common driver mutations in adenocarcinoma of the lung, and among these, the most common deletion is an in-frame, 15 bp deletion that removes bases 52–66 from this 99 bp exon (hg38 coordinates, chr7:55,174,773–55,174,787)." (PMID 31940362, 2020). "In lung adenocarcinoma, the pathway involving EGFR, ARF6 and ASAP1 was reported to be associated with reduced patient survival." (PMID 32426352, 2020). "The frequency of EGFR-driven mutations in lung adenocarcinoma rates ranges from 40% to 55% in East Asians." (PMID 32092879, 2020). "This is the first human study showing the benefit of β-blockers in patients with lung adenocarcinoma harboring EGFR mutation receiving first-line EGFR-TKIs." (PMID 33194721, 2020). "A 74-year-old woman diagnosed with T4N1M1c Stage IVB lung adenocarcinoma with EGFR mutation presented with a left upper lobe mass and multiple bilateral lung metastases." (PMID 32257480, 2020). "Recent studies have shown that the SHH pathway is upregulated in a subset of lung adenocarcinoma with EGFR mutation, and inhibition of the SHH pathway can also enhance the activity of EGFR inhibitor gefitinib in pancreatic cancer cells." (PMID 33291316, 2020). "A point mutation in exon 21 of the epidermal growth factor receptor resulting in the substitution of arginine for leucine at position 858 (L858R) is a frequent cause of lung adenocarcinoma." (PMID 33096790, 2020). "EGFR mutation is the most common genetic variant (50%–60%) in lung adenocarcinoma patients in East Asia." (PMID 32163227, 2020). "In conclusion, patients with lung adenocarcinoma harboring the EGFR S768I and G724S mutations appear less sensitive to icotinib than patients with sensitive EGFR." (PMID 32776462, 2020). "EGFR-TKIs are thus suggested as first-line therapies for stage IV EGFR-mutated lung adenocarcinoma patients, despite their PD-L1 expression levels in clinical practice." (PMID 32092879, 2020). "In recent years, EGFR targeted drugs have been widely used and achieved significant efficacy in lung adenocarcinoma, and have shown different effects in different EGFR mutation status 5-8." (PMID 32127953, 2020). "In recent years, tumor genetics was included into subtype identification, represented by the mutation status of epidermal growth factor receptor (EGFR) in lung adenocarcinoma." (PMID 33426073, 2020). "The patients with advanced lung adenocarcinoma should select targeted drugs based on the type of tumor epidermal growth factor receptor (EGFR) gene mutation." (PMID 32093452, 2020).
lung adenocarcinoma (continued). "Here, we reported a case of patient who diagnosed with multifocal lung adenocarcinomas exhibiting both EGFR mutation and EML4-ALK rearrangement, in order to give some helpful advices for the clinical practice." (PMID 32375829, 2020). "To explore the regulatory effects of B7-H3 on EGFR-TKIs treatment of lung adenocarcinoma harboring activated EGFR mutations, we administrated gefitinib to H3255 KO/mock and HCC827 KO/mock cell culture and monitored the ratio of apoptotic cells." (PMID 33426073, 2020). "ddPCR, as a high sensitivity and specificity liquid gene detection method, can be used as a reliable method to detect the mutation of plasma ctDNA EGFR gene in patients with advanced lung adenocarcinoma." (PMID 32093452, 2020). "We observed significant differences when grouping patients by sex (p < 0.001), cigarette smoking (p < 0.001), and cell differentiation (p = 0.001) in the patients with lung adenocarcinoma with the EGFR wild-type and those with the EGFR mutation type." (PMID 32344833, 2020). "BRAF mutations and translocations have been described in melanocytic nevi, malignant melanoma, colon adenocarcinoma, glioblastoma and pilocytic astrocytoma and EGFR mutations, amplifications in lung adenocarcinoma and brain tumors." (PMID 31970428, 2020). "Previous studies have shown that the Asia-Pacific patients with lung adenocarcinoma had the higher EGFR mutation frequency (47% (5958/12819)) and the Oceania patients with lung adenocarcinoma showed the lower EGFR mutation frequency (12% (69/570))." (PMID 32781755, 2020). "EGFR tyrosine kinase inhibitors (TKIs) are highly effective in patients with lung adenocarcinoma, harboring sensitive EGFR mutations." (PMID 33194721, 2020). "The mutation frequency of EGFR in adenocarcinoma of the lung within the United States is 20–30% and reaches almost 50% in patients from Asia-Pacific regions." (PMID 31940362, 2020). "The purpose of this study was to investigate outcomes of advanced lung adenocarcinomas with regard to EGFR mutation status and TKI treatment responses." (PMID 32053675, 2020). "Approximately 50%–65% of patients with EGFR-mutated lung adenocarcinoma will acquire resistance within 1 year despite initial response to TKI therapy, and eventually die of this disease; thus, a more accurate prediction tool is currently an imperative need." (PMID 33370365, 2020). "The associations among CD44 SNPs, EGFR mutations, and the clinicopathological characteristics of lung adenocarcinoma are also evaluated." (PMID 32344833, 2020). "We applied the WGCNA pipeline as well as analysis of variance (ANOVA) to identify the key protein modules and networks affected by the EGFR mutations L858R and Ex19del in patients with lung adenocarcinoma." (PMID 32616892, 2020). "The dominant mutations found frequently in lung adenocarcinomas, such as EGFR, ALK and KRAS mutations, are uncommon in SQCC." (PMID 31829519, 2020). "Thereafter, we investigated the association between EGF+61 A>G genotype and TKI response in a Brazilian series comprised of 111 TKI‐treated lung adenocarcinoma patients harboring EGFR‐sensitizing mutations." (PMID 32881389, 2020). "Lung adenocarcinomas with activating mutations in EGFR was found to produce high IL-6 levels responsible for constitutive pY705-STAT3 activity." (PMID 33279931, 2020). "Studies have found that lung adenocarcinomas sensitive to erlotinib often harbor EGFR mutations and that EGFR mutations are predictors of sensitivity to EGFR TKIs, increasing the treatment benefits; these results have recently been validated 38-41." (PMID 32929368, 2020). "We extend their findings in EGFR-mutated lung adenocarcinoma cells and further demonstrate that B7-H3 deletion increases the susceptibility of lung adenocarcinoma cells to gefitinib." (PMID 33426073, 2020). "For example, Nguyen demonstrated earlier that the WNT signaling pathway can enhance the ability of lung adenocarcinoma cells with KAS or EGFR mutation to colonize the brain." (PMID 33537237, 2020).
lung adenocarcinoma (continued). "Several prospective clinical trials have demonstrated the efficacy of EGFR tyrosine kinase inhibitors (TKI) (erlotinib and gefitinib) for the treatment of advanced lung adenocarcinoma patients with EGFR activating mutations." (PMID 33096790, 2020). "Together, these results demonstrate that B7-H3 ablation increases susceptibility of lung adenocarcinoma cells to EGFR-TKIs, especially in EGFR Del E746-A750-mutated HCC827 cells." (PMID 33426073, 2020). "First, in patients with lung adenocarcinoma harboring sensitive EGFR mutation receiving first-generation EGFR-TKIs, prior use of β-blockers was independently associated with a better 2-year TTD and 4-year OS compared with nonusers." (PMID 33194721, 2020). "Currently, only EGFR-mutated tumors are eligible to receive EGFR tyrosine kinase inhibitors, which represent only 10% of all lung adenocarcinomas." (PMID 32336282, 2020). "Further study evaluating the optimal postoperative approach for completely resected EGFR-mutant N2-positive lung adenocarcinoma is warranted in the high-risk patients." (PMID 32922551, 2020). "The combination of afatinib with bevacizumab is an effective therapy for patients with untreated stage IIIB/IV EGFR-mutated lung adenocarcinoma, and the safety of this combination is acceptable." (PMID 33113888, 2020). "Further, these studies will be necessary to translate SOS1-targeted therapies for use in EGFR-mutated lung adenocarcinoma." (PMID 32897190, 2020). "The EGFR gene is located on the short arm of chromosome 7 and contains 28 exons, and the exons 19 and 21 of EGFR are the sites of hotspot mutations in lung adenocarcinomas." (PMID 32085409, 2020). "The results of our study provided evidence that the combination of afatinib and bevacizumab was an effective and safe therapy for patients with untreated EGFR-mutated advanced lung adenocarcinoma." (PMID 33113888, 2020). "A 60-year-old man with an 8-year history of CML was diagnosed as advanced EGFR-mutated lung adenocarcinoma." (PMID 32257476, 2020). "Future prospective studies focusing on this combination for untreated advanced EGFR-mutated lung adenocarcinoma are warranted." (PMID 33113888, 2020). "The current study explored the effect of CA9 gene polymorphisms and the epidermal growth factor receptor (EGFR) mutations on the clinicopathological characters of lung adenocarcinoma." (PMID 32365566, 2020). "The combination of afatinib and bevacizumab is an effective therapy for untreated advanced EGFR-mutated lung adenocarcinoma with acceptable safety." (PMID 33113888, 2020). "The ISEL-associated IPASS trial, which identified an EGFR-activating mutation, showed that the EGFR-TKI was more effective in patients with lung adenocarcinoma, who had EGFR-TKI-sensitizing mutations (mEGFRs)." (PMID 32517757, 2020). "In this study, we aimed to pool multi-institutional data and to compare the influence of EGFR-TKI alone with that of combined radiation and TKI on the survival outcomes in TKI-naïve early-stage lung adenocarcinoma patients with EGFR mutations." (PMID 32660443, 2020). "Somatic mutations in the kinase domain of the EGFR gene are detected in approximately 40% and 17% of lung adenocarcinomas in Asians3 and Caucasians4, respectively." (PMID 32616892, 2020). "An expert dermatologist performed 35 skin biopsies from 31 patients with a confirmed diagnosis of stage IV EGFR‐mutated lung adenocarcinoma, taken by 4 mm punch in the scapular region, which was subsequently formalin‐fixed and paraffin‐embedded." (PMID 33015988, 2020). "Here, we sought to conduct a multicenter, real-world clinical data analysis of the efficacy of afatinib in combination with bevacizumab in patients with untreated EGFR-mutated advanced lung adenocarcinoma." (PMID 33113888, 2020). "We want to find an objective and molecular-based indicator to examine the effect of EGFR mutation status on the biological behavior of lung adenocarcinoma." (PMID 32127953, 2020).
lung adenocarcinoma (continued). "We find clinically relevant cases such as EGFRT790M mutation in NCI-H1975 or PTEN loss in NCI-H1650 cells, in lung adenocarcinoma treated with EGFR inhibitors." (PMID 33205120, 2020). "A female patient with lung adenocarcinoma accepted gefitinib as first-line therapy because of EGFR L858R mutation and achieved partial response." (PMID 31739500, 2019). "One sophisticated way to predict drug sensitivity is based on mutational information, such as EGFR mutation for the use of EGFR tyrosine kinase inhibitors in lung adenocarcinoma." (PMID 31108870, 2019). "Case 2: An 82-year-old woman was diagnosed with stage IV lung adenocarcinoma with an EGFR mutation (exon 21 L858R) and was treated with oral gefitinib 250 mg daily." (PMID 31764850, 2019). "The different EGFR mutations in the two lung adenocarcinomas prompted us to investigate the tumor origin, and both tumors presented as treatment-naïve mutants occurring synchronously." (PMID 31426797, 2019). "The identification of EGFR mutations in lung adenocarcinoma according to response to EGFR-targeting TKIs have found the correlation between clinical findings and prognosis in patients with lung adenocarcinomas." (PMID 30956990, 2019). "The most common genetic alterations in lung adenocarcinoma are epidermal growth factor receptor (EGFR) and KRAS activating mutations." (PMID 30741509, 2019). "Several new EGFR druggable mutations were discovered by Hotspot3D in patients with lung adenocarcinoma." (PMID 31749831, 2019). "A 55-year-old female with EGFR mutation (L858R) was diagnosed with lung adenocarcinoma, who was responsive to first-generation EGFR-tyrosine kinase inhibitor (TKI)." (PMID 31382924, 2019). "Epidermal growth factor receptor (EGFR) gene mutation is known as one of the driver mutations of lung adenocarcinoma (LUAD) and LUAD patients harboring EGFR mutation account for more than half of LUAD patients in Asia." (PMID 30800222, 2019). "Determining EGFR mutation status is important in guiding the treatment for advanced lung adenocarcinoma." (PMID 31652678, 2019). "In the 80 patients of stage III or IV lung adenocarcinoma, 51 patients had EGFR mutations detected in tissue samples, while 33 (65%) of them had concordant results shown in liquid biopsy." (PMID 31652678, 2019). "One patient did not exhibit an EGFR mutation or ALK rearrangement in the metastatic tumor, but the primary lung adenocarcinoma did carry an EGFR mutation." (PMID 31455365, 2019). "Among the erlotinib-resistant variants derived from PC9, another lung adenocarcinoma cell line harboring an EGFR-activating mutation, PC9-ER1 and -ER3 exhibited upregulated ALDH1A1." (PMID 31695757, 2019). "This is the first report of a novel mutation type EGFR-ANXA2, as well as double EGFR fusion mutations in advanced lung adenocarcinoma." (PMID 31865638, 2019). "A prospective study is necessary to establish the efficiency of CSF shunting and targeted therapy for LM-H from lung adenocarcinoma with an EGFR sensitive mutation." (PMID 30629621, 2019). "Herein, we reported for the first time the presence of intratumoral heterogeneity of the EGFR L858R mutation in lung adenocarcinoma on a single-cell level." (PMID 31014278, 2019). "Case 1: A 61-year-old man had stage IB lung adenocarcinoma with EGFR mutation (+), exon 21 L858R, and received erlotinib 150 mg daily." (PMID 31764850, 2019). "Several mechanisms determine how lung adenocarcinoma patients acquire resistance to gefitinib, including the appearance of additional EGFR mutations that lead to decreased affinity for gefitinib and amplification of the MET receptor tyrosine kinase." (PMID 30532069, 2019). "In the current study, we found that 65% of patients with newly diagnosed advanced lung adenocarcinoma harboring EGFR mutation in their tissue samples had concordant EGFR mutation testing results in the testing using liquid biopsy." (PMID 31652678, 2019).
lung adenocarcinoma (continued). "A 20-year-old woman was diagnosed with stage 4 lung adenocarcinoma with an epidermal growth factor receptor (EGFR) exon 20 insertion gene mutation." (PMID 31645848, 2019). "Liquid biopsy to identify epidermal growth factor receptor (EGFR) gene mutations from circulating tumor DNA (ctDNA) for lung adenocarcinoma is less invasive than traditional tissue biopsy." (PMID 31652678, 2019). "It has been demonstrated that the EGFR mutation rate of lung adenocarcinoma patients in Asia is ~51.4%, mainly detected in female and non-smokers." (PMID 31608233, 2019). "Recently, it was reported that high levels of NKCC1 expression predict poor clinical outcomes for lung adenocarcinoma patients and an epidermal growth factor receptor (EGFR)‐mutated subgroup." (PMID 30159893, 2019). "Activating mutations of the epidermal growth factor receptor gene (EGFR) are a driving force for some lung adenocarcinomas." (PMID 30609789, 2019). "According to the results of single-cell analysis, EGFR wild type tumor cells were detected in all six tumor samples, which suggested the existence of intratumoral heterogeneity for EGFR mutation in lung adenocarcinoma." (PMID 31014278, 2019). "Computed tomography (CT)-guided needle biopsy of the left lung revealed lung adenocarcinoma and epidermal growth factor receptor (EGFR) exon 21 L858R mutation." (PMID 31874677, 2019). "Other studies showed that the down-regulation of miRNA-145 in human lung adenocarcinoma was associated with EGFR amplification and its transfection inhibited cancer cell growth through the suppression of its targets, EGFR and NUDT-1." (PMID 31554377, 2019). "We identified 80 treatment-naïve stage III or IV lung adenocarcinoma patients during the study period, and 51 (63.75%) patients had EGFR mutation detected in their tumor tissue samples." (PMID 31652678, 2019). "As a conclusion, lung adenocarcinomas with EGFR mutations is a distinct biological subset, as evidenced by its strong association with the female and non-smoker groups." (PMID 31531095, 2019). "In Europe, 17.3% of lung adenocarcinoma tumours harbour a mutation of the epidermal growth factor receptor (EGFR)." (PMID 30612556, 2019). "Although some studies have identified an association of EGFR mutation with imaging features in lung adenocarcinomas, the results have been conflicting." (PMID 30956990, 2019). "We also for the first time reported a novel EGFRex20ins mutation, EGFR N771_P772insL, in lung adenocarcinoma." (PMID 31208370, 2019). "For instance, 50% of Asian patients and 10–15% of Caucasian patients with lung adenocarcinoma are EGFR mutation-positive, with 5% of NSCLC being ALK positive and 1% of NSCLC patients being ROS1 positive." (PMID 31766180, 2019). "Activating Epidermal Growth Factor Receptor (EGFR) mutations in western countries are found in approximately 15% of patients with lung adenocarcinomas." (PMID 30719215, 2019). "The other critical issue is how long EGFR-mutated lung adenocarcinoma achieves a long-lasting response to afatinib after treatment discontinuation." (PMID 31720896, 2019). "DESCT would be a potential tool to differentiate lung adenocarcinoma patients with a KRAS mutation from those with an EGFR mutation." (PMID 31783917, 2019). "We also analyzed the association between PD-L1 expression and clinicopathological factors in 424 EGFR mutated lung adenocarcinomas." (PMID 31561631, 2019). "Evidence also suggests that lung adenocarcinoma and lung squamous cell carcinoma differ in the composition of genes and molecular characteristics, such as EGFR gene mutations." (PMID 31475114, 2019). "Erlotinib is a first-generation EGFR-TKI for patients with EGFR mutation-positive lung adenocarcinoma." (PMID 31452776, 2019). "It has been show that HGF can induce tyrosine-kinase inhibitors resistance in lung adenocarcinoma harboring epidermal growth factor receptor (EGFR) mutations, presumably through cross-talk activation of the PI3K/AKT pathway." (PMID 31547040, 2019).